INSR (insulin receptor)
Diseases named in the same sentence as INSR in open-access papers (continued):
Sharing a sentence is not in itself a finding about the gene and the disease.
Obesity (continued). "To evaluate the role of InsR function in microglia in obesity, we used the Cre/loxP method to specifically remove the InsRs from microglial cells." (PMID 35328354, 2022). "In this regard, we demonstrated significant genetic covariance between AD and obesity at the INSR recycling gene set level." (PMID 35165256, 2022). "The role of insulin receptor (IR) activated by hyperinsulinemia in obesity-induced kidney injury is not well understood." (PMID 33400689, 2021). "The db/db mouse model used in this study is a well-established T2D model characterized by obesity, decreased insulin receptor sensitivity, and subsequent high levels of blood glucose (GLU)." (PMID 34684625, 2021). "In summary, the anti-obesity effects of rhein were considered to be related with the involvement of ERs, inflammation, oxidative stress, PPARγ, and INSR." (PMID 34516329, 2021). "Metformin significantly decreased the risk of body weight gain and increased INSR expression in F1 female offspring in PCOS-IR rats, contributing to the improvement in obesity, hyperinsulinemia, and IR." (PMID 34484117, 2021). "The specific serine protease inhibitor AEBSF attenuated systemic inflammation, obesity, and insulin resistance in diabetic mice, probably by modulating insulin receptor and cytokine expression in VAD tissue." (PMID 32015418, 2020). "A low-grade chronic inflammation ensues the pro-inflammatory activity of obesity-induced hypertrophied adipocytes and inflammatory cells, and along with increased free fatty acids they alter insulin receptor pathway, till its inhibition." (PMID 31374931, 2019). "In this review, we discuss the role of insulin and the INSR in the development and endocrine activity of adipose tissue and the pharmacological implications for the management of obesity and type 2 diabetes." (PMID 30754657, 2019). "On the contrary, selective abrogation of both INSR and IGF-IR in BAT is predisposed to obesity, severe BAT atrophy with mitochondrial dysfunction, and IR in mice fed with an obesogenic diet." (PMID 30754657, 2019). "Recent reports showed that obesity should play a major role in the pathogenesis of PCOS through the insulin, leptin and endocannabinoid receptor, and by an association between insulin receptor polymorphism and PCOS was observed." (PMID 30635060, 2019). "These include activation of neurological pathways (associated with neuroinflammation, Huntington’s disease, and axonal guidance), cardiac hypertrophy, and metabolic pathways (for example, insulin receptor signalling and leptin signalling in obesity)." (PMID 31142858, 2019). "Obesity decreased WAT abundance of InsR, the PI3K catalytic subunits (p110α and p110β), total Akt, and total GSK3 relative to the control group." (PMID 31466137, 2019). "Glycyrrhizin attenuated high-fat diet-induced obesity in Wistar rats by increasing insulin receptor expression and activating NrF2 and the homooxygenase-1 pathway." (PMID 30618749, 2018). "Methylation loci associated with obesity (AEBP2), calcium signaling (CAPNS1), insulin signaling (INSR, PTPRN2, RPTOR) and vasodilation (VASP) also appeared to be epigenome-wide significant." (PMID 29692868, 2018). "We found that most of the identified biological processes belonged to metabolic events including insulin receptor signaling, lipid metabolic process and glucose metabolic process known to be deregulated in diet-induced obesity." (PMID 27180971, 2016). "Platelets have been found to express the insulin receptor and while insulin is believed to reduce platelet sensitivity to aggregating agents, its function in IR states for example type 2 diabetes and obesity is thought to be impaired." (PMID 25880805, 2015). "To determine the role of GnRH insulin receptor signaling in the dysregulation of GnRH secretion in obesity, we created murine models of diet-induced obesity (DIO) with and without intact insulin signaling in the GnRH neuron." (PMID 25780937, 2015).
Obesity (continued). "The Ser 307, Ser 636/639, Ser 616 sites on IRS-1 have been shown to be involved in insulin receptor signaling in obesity and AD." (PMID 25978724, 2015). "Increased intramyocellular fat content in obesity and aging interferes with the phosphorylation pathway of the insulin receptor and GLUT-4 translocation." (PMID 25517117, 2014). "In support of this proposition, obesity was also related to greater expression of the phosphorylated form of the insulin receptor and total PI3K, indicating that hyperinsulinaemia induced higher stimulation of the second messengers to insulin action." (PMID 24466104, 2014). "Adipose tissue-specific insulin receptor gene knockout protects against obesity, emphasizing that insulin signaling to adipocytes is important for development of obesity." (PMID 22715406, 2012). "LAT and HAT groups were matched in age, obesity, insulin, and glucose, and had similar expression of insulin-related genes (InsR, IRS-1)." (PMID 20105310, 2010). "Novel high impact variants resulting in premature stop codons were identified in the following genes associated with enriched obesity pathways in Meishan pigs: PLIN1 (adipogenesis, white adipose tissue browning), GRB10 (insulin receptor signaling), and ACOT4 (stearate biosynthesis I)." (PMID 40340757, 2025). "In obesity, expanded adipose tissue becomes metabolically active, releasing pro-inflammatory cytokines, which interfere with insulin signaling pathways by promoting serine phosphorylation of insulin receptor substrate (IRS)." (PMID 39857741, 2025). "Obesity-related desensitization towards insulin action in adipose tissue is commonly associated with a reduced expression of the INSR, which was not the case in GHR-KO subcutaneous adipose tissue." (PMID 41125144, 2025). "Importantly, obesity-induced oxidative stress and inflammatory responses disrupt normal insulin receptor function, impairing insulin signaling and leading to IR." (PMID 40898229, 2025). "Furthermore, the miR-15 family, including miR-15a and miR-15b, has been shown to suppress INSR expression in diet-induced obesity models and human cell lines." (PMID 41385529, 2025). "However, the exact mechanisms behind impaired insulin receptor (INSR) signaling in obesity induced by a high-fat diet remain elusive." (PMID 39747658, 2025). "Central effects could be mediated via SF-1 neurones in the ventromedial hypothalamus, where selective insulin receptor knockout also induces resistance to high fat diet-induced obesity." (PMID 40152560, 2025). "It does not aim to exhaustively cover all molecular alterations linked to the pathogenesis of IR, or the advancements in understanding insulin signaling components downstream of the INSR, which may be altered in obesity." (PMID 39337290, 2024). "Notably, the loss of TNF-alpha has been linked to improved insulin sensitivity and protection against obesity-related reduction in insulin receptor signaling in obese mice." (PMID 39120321, 2024). "At a cellular level, obesity is characterized by altered cell signaling in the adipocyte, i.e., a malfunctioning of the insulin receptor (INSR)/IRS-1/Akt/AS160 pathway activation, which may result, among others, in reduced insulin-induced glucose uptake." (PMID 38794136, 2024). "An in vivo model of diet-induced obesity could also be employed to better characterize insulin receptor internalization within the brain microvasculature and cerebral blood flow." (PMID 37834116, 2023). "These obesity-related in vitro condition-induced expression changes indicate that metabolic imbalances influence insulin receptor signaling, synaptic function, and inflammatory responses in neurons and inflammatory cytokine secretion, scavenger ability, and glutamate transporters in glia." (PMID 37047207, 2023). "It has been shown in human, animal, and in vitro studies that such immunometabolic messenger crosstalk between TNFR1- and INSR-related pathways may be responsible for the induction of IR, especially in obesity and T2D." (PMID 37372966, 2023).
Obesity (continued). "Although the NPM family was found to be associated with a variety of endocrine and metabolic dysregulation, such as aerobic glycolysis, insulin receptor expression, obesity and aging, the biological functions of NPM3 were largely undefined, especially for the regulation of adipose tissue itself." (PMID 35346213, 2022). "Furthermore, SorLA overexpression in adipocytes enhances obesity by bolstering insulin receptor signaling through increased receptor recycling." (PMID 34564954, 2022). "This sex-specific decrease of POMC neurons probably can be explained by the decrease of phagocytic capacity we found in microglia-InsR-KO males in obesity, as previously it has been demonstrated that impaired microglial phagocytic capacity leads to loss of POMC neurons." (PMID 35328354, 2022). "Inverse correlation has been recently detected between increasing body mass index and decreasing insulin receptor expression and insulin signaling in visceral adipose tissue in both humans during progressing from normal to mild and severe obesity and HFD-induced model of obesity in mice as well." (PMID 35083338, 2022). "However, due to genetic or environmental factors, such as obesity, insulin receptor defects, placental hormones, and cytokine level abnormalities, IR is aggravated and becomes pathological IR." (PMID 36741990, 2022). "PPARγ and INSR play a vital role in the protective effects of rhein against HFD-induced obesity." (PMID 34516329, 2021). "Further studies, in this context, have demonstrated that IGF1R and INSR expression was restored following forced downregulation of let-7 miRNA, while a recent report of our group identified miR-128 as a hypoxia-induced miRNA, whose increase in obesity negatively affects INSR." (PMID 34681797, 2021). "Altogether, the protective effects of rhein against obesity could appear to rely on the regulation of ERs, autophagy, and inflammation, possibly also by PPARγ and INSR." (PMID 34516329, 2021). "Obesity causes ER stress that induces the UPR, which may attenuate insulin receptor signaling through hyperactivation of c-Jun N-terminal kinase and serine phosphorylation of insulin receptor substrate-1." (PMID 33066035, 2020). "Excessive insulin signaling through the insulin receptor (IR) may play a role in the pathogenesis of diet-induced metabolic disease, including obesity and type 2 diabetes." (PMID 32350271, 2020). "Furthermore, after the induction of insulin receptor knockout in mature adipocytes, iFIRKO mice were protected from subsequent obesity development through high-fat diet feeding." (PMID 31309261, 2019). "All cell lines employed in this study robustly expressed the insulin receptor, and differences in insulin receptor expression between cell lines did not correlate with obesity association or lack thereof." (PMID 31188872, 2019). "FTO (Fat mass and obesity associated gene; rs9939609), FSHB (Follicle stimulating hormone beta subunit; rs6169), FSHR (Follicle stimulating hormone receptor; rs6165/rs6166), and INSR (Insulin receptor; rs1799817) genes were genotyped using HRM assay." (PMID 30596735, 2018). "The aberrant insulin receptor signaling that occurs as a result of obesity, including Akt and mTOR signaling, is known to alter cell proliferation and growth and may mediate progressive changes in the epigenetic control of genes related to the cell cycle." (PMID 29952094, 2018). "In addition to the findings of these immune-regulatory genes, many other top associations have been implicated in obesity (AEBP2) (FDR < 0.10), calcium signaling (CAPNS1), insulin signaling (INSR, PTPRN2, RPTOR), and vasodilation (VASP)." (PMID 29692868, 2018). "Since there is an ongoing obesity epidemic, nuclear InsR, which appears to play a differential role in overweight or obese compared to normal-weight patients, warrants further investigation in an independent study, preferably in randomized clinical trials of IGF-targeting treatments." (PMID 29234306, 2017).
Obesity (continued). "Obesity changes the secretion of adipose tissue inflammatory cytokines, which modulate insulin signaling, so we analyzed the insulin signaling gene expression including insulin receptor (IR), insulin receptor substrate 1 (IRS-1), and IRS-2 in liver tissue." (PMID 29085434, 2017). "Whether the relationship between overweight/obesity and poor breast cancer prognosis is partly mediated through nuclear localization of InsR is unknown." (PMID 29234306, 2017). "Our data suggest that interventions that regulate the ERS response and insulin receptor signaling in the brain may provide novel opportunities for treating cognitive impairment induced by obesity." (PMID 25978724, 2015). "It is well established that in obesity, the uncontrolled inflammatory reaction and impairment of the host defense system, plays an important role in the inhibition of insulin receptor signaling cascade and as a direct consequence, disruption of systemic metabolic homeostasis that leads to T2D." (PMID 24986468, 2014). "NITKO mice of both sexes developed diet-sensitive obesity, increased plasma leptin levels, and increased plasma insulin level, indicating an important role for insulin receptor in the regulation of energy disposal, energy metabolism and perhaps also in reproduction." (PMID 23557393, 2013). "In contrast to mice with neuron-specific insulin receptor deletion, which only display a gender- and diet-dependent subtle increase in body weight, the obesity and glucose intolerance observed in db/db mice can be rescued by neuron-specific re-expression of ObR." (PMID 23554574, 2013). "BAIAP2L1 is also known as IRTKS (insulin receptor tyrosine kinase substrate) which is involved in insulin receptor signaling and may relate to insulin resistant states including obesity and T2D." (PMID 22829776, 2012). "Moreover, a myeloid lineage-specific InsR-KO mouse (MphIRKO) exhibited reduced atherosclerotic lesion size in the descending aorta compared to control mice, indicating that insulin/InsR signaling in macrophages promoted obesity-induced atherosclerotic lesion formation." (PMID 40868889, 2025). "Thus, ablation of the placental InsR may have health beneficial effects in the male offspring of multiparous dams, where they often present higher obesity and hyperinsulinemia." (PMID 35327377, 2022). "While we are careful in the interpretation of this analysis, deletion of the placental insulin receptor may potentially be associated with a mild protective effect against diet-induced obesity and glucose homeostasis dysfunction in male InsR KOplacenta offspring when challenged with a HFD." (PMID 35327377, 2022). "In the present study, we explored the role of the placental insulin receptor in a normal mouse pregnancy using a preclinical model, and our results suggest that placental InsR may contribute to the long-term offspring health when metabolically challenged with diet-induced obesity." (PMID 35327377, 2022). "Insulin resistance syndrome including obesity, hyperglycemia, hyperlipidemia, and hypertension or insulin therapy in our donors might interfere with the insulin signaling pathway, leading to alteration of the INSR function." (PMID 31781030, 2019). "However, the relationship between ERS and insulin receptor signaling in the brain during obesity remains unclear." (PMID 25978724, 2015). "Thus, the defect in insulin receptor signaling in Bbs4-/- mice is not related to obesity, but rather due to loss of BBS4 protein." (PMID 26103456, 2015). "TNFα plays a main role in the inflammatory state that is characteristic of obesity, and the increase in its levels may be related with the inhibitory effect on insulin receptor signalling pathway, the diminishing triacylglycerol depots in adipose tissue or in the development of apoptosis." (PMID 17725831, 2007).
Obesity (continued). "Elevated free fatty acids in obesity promote ectopic lipid storage, activating atypical PKC isoforms that disrupt insulin receptor signaling, impairing glucose uptake in muscle and reducing hepatic glycogen synthesis." (PMID 40699839, 2025). "Nonetheless, evidence suggests that obesity drives an increase in hs-CRP levels, which in turn hinders insulin receptor activation." (PMID 38982554, 2024). "Insulin-stimulated phosphorylations of INSR, IRS-1, Akt2, and GSK3β were markedly reduced in the liver of HFD-fed mice, indicating that HFD-induced obesity impaired hepatic insulin signaling." (PMID 35328400, 2022). "Studies have proved that high level of BCAAs in plasma can continuously activate the mTOR signaling pathway and disassociate insulin receptor from insulin receptor substrate 1, which is closely related to the occurrence of T2DM and obesity." (PMID 34149613, 2021). "Dopamine directly acts in the same tissues to regulate InsR, Akt, and AMPK phosphorylation, being also involved in the regulation of metabolic functions in WAT, which can be an important factor for obesity-related diseases." (PMID 34566639, 2021). "In the context of obesity and diabetes perhaps the best understood functions of AKT signalling are those downstream of insulin receptor activation." (PMID 31765625, 2020). "Conversely, increased A2BP1 expression was found in obesity, Also, this gene interacted with ATXN2, INSR, and MC4R, which played important roles in metabolic pathways." (PMID 30547318, 2019). "The proportion of POMC neurons activated by insulin was dependent on the regulation of insulin receptor signaling by the phosphatase TCPTP, which is increased by fasting, degraded after feeding and elevated in diet-induced obesity." (PMID 30230471, 2018). "Next, we determined the molecular relationship between insulin receptor signaling and striatal DAT surface expression and function in a diet-induced obesity (DIO) model." (PMID 29698491, 2018). "Dysregulation of these kinases due to obesity disrupts the interaction between IRS and insulin receptor (IR), which leads to impairment in insulin signaling." (PMID 30131766, 2018). "The neuron-specific insulin receptor knockout (NIRKO) mice resulted in increased food intake and moderate diet-induced obesity, demonstrating the anti-obesity role of insulin." (PMID 26956881, 2016). "Finally, after showing that DEP-1 was differentially regulated in metabolic tissues in diet-induced obesity, and that DEP-1 significantly impacts on insulin signaling, we addressed whether DEP-1 physically associates with the insulin receptor by recruitment studies applying PLA." (PMID 23889985, 2013). "Another study in rats showed that a maternal HFD led to hypermethylation of the hypothalamic InsR in male offspring but not female, leading to hyperleptinemia, hyperinsulinemia, impaired glucose tolerance, increased insulin resistance, and obesity." (PMID 41040868, 2025). "Overall, these data suggest that high circulating levels of insulin (and/or other adiposity hormones, like leptin) in obesity can lead to striatal InsR insensitivity, independent of the caloric source used to induce obesity." (PMID 36979453, 2023). "Obesity and its characteristics, such as excess visceral fat, chronic inflammation, and reactive oxygen species, are responsible for IR in obese women with PCOS by increasing the impaired insulin receptor-related signaling pathways." (PMID 37347114, 2023). "Here we report that lack of microglial insulin signaling in obesity impaired insulin sensitivity in female mice, which suggests a protective role of intact microglial InsR function in obese females." (PMID 35328354, 2022). "During obesity the phenotypic deviation of M2 to M1 macrophages in adipose tissue increases the production of proinflammatory cytokines such as TNF-α and IL-6, which inhibit the insulin receptor signaling." (PMID 32774333, 2020).